ZNF256 (zinc finger protein 256)
Description:
Transcriptional repressor that plays a role in cell proliferation. Requires TRIM28 for its activity.
Synonyms: BMZF-3; BMZF3
Tractability: PROTAC: ubiquitination databases record sites on it.
Gene: Protein-coding gene on chromosome 19 (57,940,833 to 57,947,706, reverse strand). Ensembl gene ENSG00000152454.
Subcellular location: Nucleus
Subcellular location (Human Protein Atlas): Nucleoplasm
Pathways (Reactome):
Gene expression (Transcription): Generic Transcription Pathway
Gene Ontology:
Molecular function: protein binding; DNA-binding transcription factor activity, RNA polymerase II-specific; RNA polymerase II cis-regulatory region sequence-specific DNA binding
Biological process: negative regulation of DNA-templated transcription; regulation of transcription by RNA polymerase II; regulation of DNA-templated transcription
Cellular component: nucleoplasm; nucleus
Genetic constraint (gnomAD): Loss-of-function variants: 2 observed, 4.65 expected, observed/expected ratio (o/e) 0.43, 90% interval 0.17 to 1.33. That is too few expected variants to judge how well the gene tolerates losing a copy. Missense variants: 642 observed, 757.69 expected, observed/expected ratio (o/e) 0.85, 90% interval 0.79 to 0.9. Synonymous variants: 250 observed, 258.52 expected, observed/expected ratio (o/e) 0.97, 90% interval 0.87 to 1.07.
Homologues: Orthologues: chimpanzee ZNF256 (99% identical), macaque ZNF256 (97% identical), tropical clawed frog zfx (18% identical), mouse Zfy1 (18% identical), rat Zfy1 (17% identical), zebrafish zfx (17% identical), mouse Zfy2 (17% identical). Paralogues in human: ZNF551 (48% identical), ZNF154 (47% identical), ZNF304 (47% identical), ZNF792 (47% identical), ZNF418 (47% identical), ZNF587B (46% identical), ZNF548 (42% identical), ZNF549 (42% identical), ZIK1 (41% identical), ZNF772 (40% identical), ZNF773 (38% identical), ZNF419 (36% identical), and 26 more.
Diseases named in the same sentence as ZNF256 in open-access papers:
ZNF256 is named in the same sentence as 2 diseases in open-access papers, as found by Europe PMC text mining. Sharing a sentence is not in itself a finding about the gene and the disease.
ZNF256 shares sentences with these, for which no sentence is quoted: cardiovascular diseases (1 paper); lung diseases (1).